DNMT3B (DNA methyltransferase 3 beta)
Diseases named in the same sentence as DNMT3B in open-access papers (continued):
Sharing a sentence is not in itself a finding about the gene and the disease.
chronic hepatitis (3 papers, 2019 to 2024). An active inflammatory process affecting the liver for more than six months. "We explored the role of Dnmt3b on chronic hepatitis and hepatocarcinogenesis using a novel Dnmt3b-deficient mouse model through deletion of exons 15–19, including the PC motif (exon 18) and ENV motif (exon 19), which are essential for methylation activity." (PMID 33277576, 2020). "First, we examined the expression level of DNMT3B in normal liver tissues, chronic hepatitis tissues, cirrhotic liver regenerative nodules (RNs) and HCC tissues." (PMID 33277576, 2020). "In the current study, we focused on the role of DNMT3B in regulating the DNA methylation pattern on the development of chronic hepatitis and HCC." (PMID 33277576, 2020). "To determine the role of Dnmt3b in long-term chronic hepatitis, we extended the duration of TAA treatment (0.02% in drinking water) up to 30 weeks." (PMID 33277576, 2020). "Our findings indicate that Dnmt3b plays an important role in protecting hepatocytes in chronic hepatitis." (PMID 33277576, 2020). "In summary, using a novel mouse model, we demonstrated that Dnmt3b depletion in hepatocytes exacerbated inflammation in chronic hepatitis leading to accelerated fibrosis and carcinogenesis." (PMID 33277576, 2020). "The number of methylated genes and the mRNA levels of DNMT1, DNMT3a and DNMT3b were shown to be increased progressively from normal liver, chronic hepatitis/cirrhosis to HCC." (PMID 31771617, 2019). "However, it still remains to be elucidated how the dysregulated DNMT3B contributes to HCC development in patients with chronic hepatitis." (PMID 33277576, 2020).
chronic lymphocytic leukemia (3 papers, 2016 to 2022). "For instance, along with DNMT3A, DNMT3B belongs to the top 1% of underexpressed genes in human chronic lymphocytic leukemia (CLL)." (PMID 33450231, 2021).
Cirrhosis (3 papers, 2019 to 2024). A chronic disorder of the liver in which liver tissue becomes scarred and is partially replaced by regenerative nodules and fibrotic tissue resulting in loss of liver function. "We revealed that the loss of Dnmt3b exacerbated hepatitis and promoted the progression of fibrosis, cirrhosis, and carcinogenesis in the inflamed liver; however, Dnmt3b deletion exhibited less effect on liver tissues without inflammation." (PMID 33277576, 2020).
cognitive decline (3 papers, 2016 to 2021). "It was also found that intracerebroventricular injection of miR-29c mimic into 5xFAD mice prevented cognitive decline, as well as neuronal loss in the subiculum area, by down-regulating Dnmt3a and Dnmt3b in the hippocampus." (PMID 34750393, 2021). "HDAC4 is implicated in both age- and Alzheimer disease-associated cognitive decline and DNMT3B in cognitive ability of psychotic patients and healthy subjects." (PMID 30377985, 2019). "Recently, it is has been reported that DNMT3b moderates cognitive decline in subjects with mild cognitive impairment." (PMID 27013617, 2016).
Cognitive impairment (3 papers, 2016 to 2025). Abnormal cognition is characterized by deficits in thinking, reasoning, or remembering. "The limited expression of Dnmt3b to neural progenitor cells and the mild cognitive defects seen in ICF patients suggest that DNMT3B may be crucial for early neurogenesis." (PMID 40469903, 2025). "It was found that the up-regulation of miR-29c prevented cognitive impairment in 5xFAD mice, possibly by inhibiting the expressions of DNMT3A, DNMT3B, and BACE1 in the hippocampus." (PMID 34750393, 2021).
Down syndrome (3 papers, 2019 to 2023). "Of particular interest are disorders such as Down syndrome, lung and gastrointestinal cancers, and male infertility, all linked to DNMT3B variants and characterized by MTHFR hyper-methylation." (PMID 31370354, 2019). "We found that the DNMT3B rs2424913 TT genotypes and the genetic model CC + CT vs. TT could be predisposing factors for CHDs in individuals with Down syndrome and particularly those with ASDs." (PMID 36980848, 2023). "The aim of this study was to investigate the association between the MTHFR rs1801133, MTHFR rs1801131, MTRR rs1801394, DNMT1 rs2228611, DNMT3A rs1550117, DNMT3B rs1569686, and DNMT3B rs2424913 gene polymorphisms and congenital heart defects in Down syndrome (DS) individuals." (PMID 36980848, 2023). "Furthermore, three independent studies found DNMT3B rs1569686 and rs2424913 to be maternal risk factors for Down syndrome, again confirming the importance of DNMT3B gene polymorphisms in human reproduction." (PMID 32118373, 2020). "DNMT3L gene variants affected birth-weight and were associated with male infertility and ovarian endometriosis, while maternal DNMT3B SNPs increased the risk for PTB and Down syndrome." (PMID 32118373, 2020).
folate deficiency (3 papers, 2019 to 2020). A nutritional condition produced by a deficiency of FOLIC ACID in the diet. "B12 over-supplementation in combination with folate deficiency (BOFD) led to an increase in the mRNA levels of DNMT3B in all tissues along with an increase in the placenta in BOFO group and decrease in the brain in BOFN group as compared to control (BNFN)." (PMID 31772242, 2019). "B12 deficiency in combination with folate deficiency (BDFD) increased transcript levels of DNMT3B whereas in combination with folate normal (BDFN) levels were decreased in the brain and increased in the liver as compared to BNFN." (PMID 31772242, 2019). "Folate deficiency (FD) increased in the transcript levels of DNMT3B however, with folate over-supplementation (FO) transcript levels were not changed in the brain (male) when compared to folate normal (FN)." (PMID 31772242, 2019). "B12 deficiency in combination with folate deficiency (BDFD) resulted in an increase in levels of DNMT3B in all the fetal tissues regardless of sex whereas no change was observed with folate normal (BDFN) as compared to BNFN." (PMID 31772242, 2019).
hepatoblastoma (3 papers, 2024 to 2025). Hepatoblastoma (HB) is a malignant hepatic tumor and is the most common pediatric liver cancer. "In this study, we identified dual overexpression of PFKFB4 and DNMT3B in hepatoblastoma patient samples with metastatic risk (high-risk CHIC stratification), based on the metabolic enzyme expression program of hepatoblastoma tumors." (PMID 39595571, 2024). "This study identified the dual overexpression of PFKFB4 and DNMT3B in hepatoblastoma patients at risk of metastasis (high-risk CHIC classification)." (PMID 39595571, 2024). "Our study identifies DNMT3B and PFKFB4 as genes associated with metastatic characteristics in hepatoblastoma, suggesting them as potential biomarkers that require further investigation." (PMID 39595571, 2024). "This work highlights the complex interplay between metabolic reprogramming and epigenetic dysregulation in hepatoblastoma, particularly through the overexpression of DNMT3B and the involvement of one-carbon metabolism in tumor cells." (PMID 39684755, 2024). "This study reveals a complex interplay between metabolic reprogramming and epigenetic dysregulation in hepatoblastoma, as demonstrated through transcriptomic analysis highlighting the overexpression of DNMT3B and the implications of one-carbon metabolism in tumor cells." (PMID 39684755, 2024). "Our study, which utilized the Mammalian Metabolic Enzyme Database, led to the development of a metabolic score based on the combined expression of DNMT3B and PFKFB4 in hepatoblastoma." (PMID 39595571, 2024). "While our study identified DNMT3B and PFKFB4 as individual predictive biomarkers of metastasis in hepatoblastoma, it is also possible that these two proteins interact or influence each other’s functions." (PMID 39595571, 2024). "The combined tumor expression of DNMT3B and PFKFB4 was used to compute a metabolic score, which was validated as an independent predictor of metastatic status in hepatoblastoma." (PMID 39595571, 2024). "A meta.score, computed from the combined tumor expression of DNMT3B and PFKFB4, was confirmed as an independent adverse predictor of metastatic status in hepatoblastoma." (PMID 39595571, 2024). "We used a univariate analysis to demonstrate that the meta.score, derived from the combined expression of DNMT3B and PFKFB4, can predict metastasis status in hepatoblastoma tumors." (PMID 39595571, 2024). "In conclusion, our study has identified DNMT3B and PFKFB4 as potential individual biomarkers of metastasis in hepatoblastoma." (PMID 39595571, 2024). "Notably, the transcriptional expression of DNMT3B, followed by PFKFB4 and SOD3, was identified as the most strongly correlated with positive metastatic status in hepatoblastoma." (PMID 39595571, 2024). "A significant difference in DNMT3B expression was indeed confirmed between hepatoblastoma (HB) tumors with negative and positive metastasis status by computational analysis (two-sided t-test p-value = 0.007)." (PMID 39595571, 2024).
immune thrombocytopenic purpura (3 papers, 2013 to 2022). "DNMT3B promoter polymorphisms have been reported to be associated with the risk of immune thrombocytopenic purpura (ITP) and malignant solid tumors, such as colorectal cancer, lung cancer, and breast cancer, albeit to varying degrees." (PMID 24069326, 2013).
immunodeficiency-centromeric instability-facial anomalies syndrome 1 (3 papers, 2021 to 2025). Any immunodeficiency-centromeric instability-facial anomalies syndrome in which the cause of the disease is a mutation in the DNMT3B gene. "In humans, mutations in DNMT3B have been linked to Immunodeficiency-Centromeric Instability-Facial Anomalies Syndrome 1 (ICF1; OMIM 242860)." (PMID 40469903, 2025).
Intellectual disability (3 papers, 2017 to 2024). "Mutations in DNMT1 are associated with neuropathies, mutations in DNMT3A cause overgrowth syndromes with intellectual disability, and DNMT3B mutations are involved in immunodeficiency and intellectual disability." (PMID 35997367, 2022).
invasive breast carcinoma (3 papers, 2014 to 2019). A carcinoma that infiltrates the breast parenchyma. "Results showed that the expression level of DNMT3B mRNA was upregulated in invasive breast carcinoma, ductal breast carcinoma, and invasive ductal breast carcinoma." (PMID 29796115, 2018). "Overexpression of DCAF13, DNMT3B, KPNA2, EXO1, FANCI, RACGAP1, and ZNF106 in invasive breast carcinoma patients showed poor survival, while overexpression of CDKN2A, SORBS1, and TP63 showed better survival." (PMID 32010179, 2019).
pulmonary hypertension (3 papers, 2022 to 2025). Increased pressure within the pulmonary circulation due to lung or heart disorder. "In that regard, a recent study suggests expression of DNMT3b increases and other DNMTs decrease in lungs of congestive heart disease‐associated PAH, and knockdown of Dnmt3b in rats augments monocrotaline and hypoxia induced pulmonary hypertension." (PMID 35581740, 2022). "In patients with pulmonary hypertension, a condition with life-threatening implications, DNMT3B expression is increased in vascular smooth muscle cells." (PMID 39819598, 2025). "Indeed, Dnmt3b knockout rats showed facilitated development of pulmonary hypertension, a phenotype that could be prevented by overexpression of the gene." (PMID 39819598, 2025). "A recent study found upregulated DNMT1 and DNMT3B expression and increased DNMT activity in the lungs of rats with sugen5416/hypoxia-induced pulmonary hypertension." (PMID 37947606, 2023).
retinoblastoma (3 papers, 2017 to 2025). A malignant tumor that originates in the nuclear layer of the retina. "The study also mentions the connection between BIRC5 (survinin) and DNA methylation in retinoblastoma regulated by Dnmt1, Dnmt3a, and Dnmt3b." (PMID 41150792, 2025). "In support of this possibility, DNMT3A and DNMT3B were found to be highly expressed in Y79 and primary retinoblastoma." (PMID 28467809, 2017).
triple-negative breast carcinoma (3 papers, 2019 to 2024). An invasive breast carcinoma which is negative for expression of estrogen receptor (ER), progesterone receptor (PR), and human epidermal growth factor receptor 2 (HER2). "Thus, we also assessed the expression of DNMT3B and ALYREF in luminal, HER2 positive, and triple negative breast cancer." (PMID 35812757, 2022).
Arthritis (2 papers, 2017 to 2019). Inflammation of a joint. "Less significance seems to have changes in the DNMT3B mRNA level changes associated with arthritis, because according to our results, this enzyme plays only a supporting role in methylation in PBMCs." (PMID 28349196, 2017). "Furthermore, individuals with arthritis (9 patients, 28.1%) were found to have significantly lower levels of DNMT3B mRNA levels (p = 0.029297) than patients without arthritis." (PMID 28349196, 2017).
asthma (2 papers, 2019 to 2021). "It was concluded that DNMT3a and DNMT3b mediated de novo methylation of miR-23b promotor, which plays a vital role in EMT and airway remodeling in asthma." (PMID 35058921, 2021).
atrial septal defect (2 papers, 2023). Interauricular communication is a congenital malformation characterized by a communication between the atrial chambers of the heart. "The DNMT3B rs2424913 TT genotype, as well as the T allele, had significantly higher frequencies in the individuals with DS and atrial septal defects (ASDs) in comparison with the individuals with DS and other CHDs." (PMID 36980848, 2023). "Finally, the DNMT3B rs2424913 TT genotype was associated with CHDs, specifically atrial septal defects, in individuals with Down’s syndrome, suggesting that this genotype may be a predisposing factor and biomarker for CHDs in these individuals." (PMID 37947606, 2023).
biliary atresia (2 papers, 2018 to 2019). A rare, biliary tract disease characterized by progressive obliterative cholangiopathy of the intra- and extrahepatic bile ducts, occurring in the embryonic/ perinatal period, leading to severe and persistent neonatal jaundice and acholic stool. "We found the overexpression of miR-142-5p and mRNA level of DNA methyltransferase (DNMT) 1, and miR-29b and DNMT3a/DNMT3b were significantly negatively correlated in biliary atresia livers." (PMID 29748604, 2018). "Our study showed that DNMT1, DNMT3a, and DNMT3b expression is significantly decreased, while the expression level of IFN-γ is increased in liver samples of biliary atresia cases." (PMID 29748604, 2018).
Bladder Urothelial Carcinoma (2 papers, 2020). "For example, DNMT3B-mediated methylation of the metastasis suppressor 1 (MTSS1) promoter epigenetically suppresses MTSS1 transcription in the urothelial carcinoma of the bladder." (PMID 33221743, 2020).
choriocarcinoma (2 papers, 2021 to 2022). An aggressive malignant tumor arising from trophoblastic cells. "Choriocarcinoma tumor cells were found to significantly overexpress DNA methyltransferase 3 beta (DNMT3B), which is the enzyme involved in de novo methylation of DNA during development." (PMID 35681761, 2022). "Besides, DNMT1 and DNMT3b were negatively correlated with miR-497-5p in eight choriocarcinoma tissues." (PMID 34732693, 2021).
chronic myelogenous leukemia (2 papers, 2013 to 2021). "AML and chronic myelogenous leukemia (CML) cells in the acute phase also showed increased expression levels for DNMT1, DNMT3A and DNMT3B when compared to normal bone marrow cells." (PMID 23638630, 2013).
colorectal adenoma (2 papers, 2016 to 2017). An adenoma that arises from the colon or rectum. "Dnmt3a suppresses K-Ras-driven lung tumor progression, whereas Dnmt3b is pro-tumorigenic in APC-deficient colorectal adenomas." (PMID 28425913, 2017). "The data are related to the research article “Gene-specific DNA methylation of DNMT3B and MTHFR and colorectal adenoma risk” in Mutation Research – Fundamental and Molecular Mechanisms of Mutagenesis." (PMID 26759827, 2016).
cutaneous melanoma (2 papers, 2016 to 2023). A primary melanoma arising from atypical melanocytes in the skin. "In cutaneous melanoma, down-regulation of miR-29c has been associated with an adverse prognosis, attributed in part to its regulation of transcripts for the DNA methyltransferases DNMT3A/DNMT3B." (PMID 27852308, 2016). "We also found that RARA-AS1 was significantly correlated with all methyltransferase genes (DNMT3B, DNMT3A, TRDMT1, and DNMT) in KIRC, LGG, Skin cutaneous melanoma (SKCM), and UVM." (PMID 37833349, 2023).
facioscapulohumeral muscular dystrophy (2 papers, 2017 to 2025). An autosomal dominant disorder affecting the skeletal muscles of the face, scapula, and upper arm. "Facioscapulohumeral muscular dystrophy (FSHD) is in most cases caused by a contraction of the D4Z4 macrosatellite repeat on chromosome 4 (FSHD1) or by mutations in the SMCHD1 or DNMT3B gene (FSHD2)." (PMID 28587678, 2017).
fibrosis (2 papers, 2020 to 2024). the formation of excess fibrous connective tissue in an organ or tissue in a reparative or reactive process. "Pathological examination, however, revealed that liver fibrosis was more evident in the Dnmt3b-deficient mice." (PMID 33277576, 2020). "In this analysis, hepatic expression of DNMT1, DNMT3a, and DNMT3b was significantly increased in individuals with fibrosis as compared to a control group of healthy individuals." (PMID 38722973, 2024).
glucose metabolism disorder (2 papers, 2023 to 2025). "We subsequently discovered that miR-548ag is upregulated in obese individuals and contributes to glucose metabolism disorders by targeting DNMT3B, thereby upregulating DPP4 expression in the liver." (PMID 40339699, 2025).
Hepatic steatosis (2 papers, 2020 to 2026). Steatosis is a term used to denote lipid accumulation within hepatocytes. "This activation inhibits endotoxin translocation and induces hepatic DNMT3B-mediated epigenetic reprogramming to reverse hepatic steatosis." (PMID 41918527, 2026).
injury (2 papers, 2024 to 2025). Damage inflicted on the body as the direct or indirect result of an external force, with or without disruption of structural continuity. "In an experimental model of traumatic brain injury, T3 administration increased the expression of Tet family genes and decreased the expression of DNA methyltransferases (Dnmt) 3a and Dnmt3b, blocking hypoxia-induced DNA methylation which reduced neuronal damage and prevented apoptosis." (PMID 40868949, 2025).
laryngeal carcinoma (2 papers, 2020 to 2025). Carcinoma that arises from the laryngeal epithelium. "Furthermore, it is the first study investigating expression of DNMT3A and DNMT3B in patients with laryngeal cancer, and it is the first study investigating DNMT1 in locally advanced LSCC." (PMID 40507223, 2025).
lung disease (2 papers, 2017 to 2022). "Because DNMT1 and DNMT3B expression tend to increase in arteries and alveoli, we anticipate total differential methylation occurred in the lungs (including arteries, airway, and alveoli) contributed to the pathogenesis of pulmonary disease." (PMID 36372233, 2022).